APOE (apolipoprotein E)
Diseases named in the same sentence as APOE in open-access papers (continued):
Sharing a sentence is not in itself a finding about the gene and the disease.
atherosclerosis (continued). "Next, to determine the effect of WD and atherosclerosis development on B and T cells in aorta and PVAT, 8 week old ApoE−/− mice were fed 12 weeks of WD and flow cytometry for B and T cells was performed." (PMID 28970806, 2017). "Dyslipidemia and hepatic steatosis were recognized as the early events of atherosclerosis; after 15-week supplementation, GTP improved the dyslipidemia and hepatic steatosis in ApoE-knockout mice." (PMID 28777810, 2017). "Considering that OSMR-β expression was significantly increased in the aortas of ApoE−/− mice fed a HFD, we proposed that endogenous OSMR-β plays a critical role in the development of atherosclerosis." (PMID 28258089, 2017). "Our results suggest the need for further investigation on the possible influence of FOXO3A/FNDC5 interactions and APOE/FNDC5 interactions with EL, but also with other age-related diseases such as atherosclerosis, Alzheimer’s, or Parkinson’s disease." (PMID 29143599, 2017). "In this study, we prepared ApoE KO mice treated with both nicotinamide and streptozotocin (NA/STZ) as a diabetic and a hyperlipidemic rodent model exhibiting rapid progression of atherosclerosis." (PMID 28777298, 2017). "On the other hand, Rae-1ε, which is also called Raet-1ε, is reported to be decreased in atherosclerotic plaques in ApoE−/− FVB mice fed with AIN76a diet for 16 weeks, and transgenic mice of Rae-1ε show decreased atherosclerosis development." (PMID 27045575, 2016). "Indeed, it is not surprising that the genetic deletion of either SR‐A1 or CD36 has no beneficial effects in ApoE‐deficient mice 38, 39 because oxLDL uptake by macrophages could be compensated by SR‐BI (in early atherosclerosis) and LOX‐1." (PMID 26493158, 2016). "Male SIRT6+/−; ApoE−/− mice and their littermate controls male SIRT6+/+; ApoE−/− mice at 8-weeks of age were put on a HFD for 8 additional weeks to accelerate atherosclerosis development." (PMID 27249230, 2016). "Taken together, we provide strong evidence that 3-MA can inhibit atherosclerosis development and improve plaque stabilization in HFD-fed ApoE−/− mice." (PMID 27906187, 2016). "A previous study used an ApoE−/− mouse model, which is important for studying the mechanisms by which LDL, as a sole mediator, induces atherosclerosis." (PMID 27430968, 2016). "Apolipoprotein E knockout (apoE−/−) and low-density lipoprotein receptor (LDL-R−/−) mice develop hypercholesterolemia and atherosclerosis spontaneously or under a high cholesterol diet, respectively." (PMID 27321128, 2016). "Consequentially, compared to STZ-injected diabetic ApoE-/- mice, UDCA-treated diabetic mice experienced significant reductions in atherosclerosis." (PMID 26807573, 2016). "Diabetic ApoE−/− mice exhibited a significant increase in plaque area at the level of the aortic arch and the proximal aorta compared to controls, but it is difficult to discriminate whether the accelerated atherosclerosis is due to hyperglycemia or dyslipidemia." (PMID 27618031, 2016). "For this purpose, we employed transgenes for human APOE-Leiden and CETP, both of which had been previously used to promote atherosclerosis development in mice in a dominant manner." (PMID 26694027, 2015). "To examine the effects of APN secreted by perivascular adipose tissue on the development of atherosclerosis, we firstly performed the site-controlled atherogenesis on the C57/BL6 wild-type mice and the ApoE-/- mice by perivascular collar placement." (PMID 26020520, 2015). "Our previous study indicated that CUMS dramatically accelerated atherosclerosis and elevated TLR4 and NF-κB in apoE-/- mice." (PMID 25860573, 2015).
atherosclerosis (continued). "To address the pathophysiological roles of TLR4/NF-κB signaling in the development of atherosclerosis induced by CUMS, we evaluated the influence of TLR4 knockdown and NF-κB inhibition on the atherosclerosis in apoE-/- mice." (PMID 25860573, 2015). "We have defined mechanisms involved in the beneficial effects of Illicium v. on atherosclerosis plaque lesions by investigating effects of the agent on anti-inflammatory responses in HASMCs in vitro, and in aortas of HFD-fed ApoE−/− mice in vivo." (PMID 26174316, 2015). "In apoE-/- mice, which have a reduced glomerular filtration rate compared with wild type controls, the ensuing CKD accelerates atherosclerosis and increases thickening of aortic valves." (PMID 25799529, 2015). "In another study, double knockout mice for ApoE and TLR4 (ApoE−/−/TLR4−/−) also showed markedly reduced atherosclerosis and altered plaque phenotype, despite persistent hypercholesterolemia." (PMID 25757594, 2015). "PGRN has protective functions in atherosclerosis, as PGRN and ApoE double KO mice showed severe atherosclerotic lesions compared with ApoE KO mice." (PMID 26408020, 2015). "Animal studies using a xenograft mice model and ApoE KO mice fed a high-fat diet further supported the link among oxLDL, miR-210, and SPRED2 in relation to tumorigenesis and atherosclerosis." (PMID 26254226, 2015). "In apoE-/-;PDZK1-/- mice, receipt of a Paigen diet results in further exaggeration of atherosclerosis with macrophage-rich lesions and occlusive coronary artery disease in association with extreme hypercholesterolemia." (PMID 25886360, 2015). "Moreover, we could show that increased arterial stiffening was causal for lesion formation because pharmacologic inhibition of collagen-I crosslinking in apoE-null mice reduced arterial stiffness and atherosclerosis in apoE-null mice despite elevated cholesterol." (PMID 26068461, 2015). "Although the level of APOE could play a protective role against various forms of vascular disease, including atherosclerosis and injury-induced restenosis, we did not observe a significant correlation between the APOE*2, *3, and *4 polymorphisms and the risk of ISR." (PMID 26497592, 2015). "In the context of atherosclerosis, the role of specific NADPH oxidase subunits has been investigated principally using the ApoE−/− mice, the most widely studied animal model of the disease." (PMID 25866599, 2015). "Murine atherosclerosis model, crossing the CD36-null mouse into an apolipoprotein E-null atherogenic strain developed significantly less atherosclerosis." (PMID 26633327, 2015). "Our previous studies have shown that chronic unpredictable mild stress (CUMS) accelerates atherosclerosis and up-regulates TLR4/NF-κB expression in apoE-/- mice." (PMID 25860573, 2015). "ANXA7 also participated in the progression of atherosclerosis and targeting ANXA7 inhibited atherosclerosis in apoE−/− mice." (PMID 24864152, 2014). "The suppression of atherosclerosis in apolipoprotein E knockout mice by lentivirus-mediated CHI3L1 gene silencing suggests a role of YKL-40 on plaque progression and as a candidate therapeutic target in atherosclerosis." (PMID 25486056, 2014). "In vivo studies, atherosclerosis animals were established using balloon-aortic denudation (BAD) rats and ApoE-/- mice fed with high-caloric diet (HCD) for 17 or 14 weeks respectively, and atherosclerotic plaques were evaluated by oil red staining." (PMID 24465540, 2014). "In ApoE knock-out mice, IFN-γ was shown to potentiate atherosclerosis through both local and systemic effects." (PMID 24383855, 2014). "In summary, our study confirms that sitagliptin can attenuate the development of atherosclerosis and alter the composition of the atherosclerotic plaques induced by HFD in ApoE-/- mice." (PMID 24490809, 2014).
atherosclerosis (continued). "On the other hand, the standard murine models for atherosclerosis, LDL receptor knockout (KO) and apolipoprotein E (apoE) KO mice, which exhibit atherosclerotic lesions in the aorta, do not usually develop MI." (PMID 23950999, 2013). "Our study in apoE−/− mice showed that BA inhibited NF-κB activation and increased circulating HDL-C, reduced TC and LDL-C, and regressed established atherosclerosis." (PMID 24086374, 2013). "To experimentally simulate clinical presentation of atherosclerosis in ApoE−/− mice, we fed the mice a HFD for 6 weeks to establish atherosclerosis." (PMID 23560095, 2013). "Our previous study demonstrated that chronic treatment of ApoE−/− mice with the TRPV1 agonist evodiamine alleviated hyperlipidemia, systemic inflammation, hepatic macrovesicular steatosis, and atherosclerosis." (PMID 23878415, 2013). "Interestingly, treatment of cold-exposed ApoE−/− mice with acipimox and simvastatin resulted in a similar antiatherosclerotic effect, suggesting that lipolysis and cholesterol synthesis are cohesively coupling processes that contribute to cold-induced atherosclerosis." (PMID 23823482, 2013). "Moreover, atherosclerosis was accelerated in HO-1 absent/apolipoprotein E-deficient (ApoE−/−) mice." (PMID 23691261, 2013). "The gld.apoE−/− model is ideal to use for this experiment based on previous findings of synergistic disease presentation of both SLE and atherosclerosis in mice." (PMID 23577189, 2013). "Angiotensin II (AngII) infusion is commonly used to promote atherosclerosis and AAA in ApoE−/− mice." (PMID 23469284, 2013). "In the present study, we observed similar staining for GzmA in the plaques of ApoE KO, GzmB/ApoE DKO and Prf1/ApoE DKO mice.The exact role of GzmA and its influence on inflammation and plaque development in atherosclerosis remains to be investigated." (PMID 24205352, 2013). "Consistent with the change in lipid profile, western diet in ApoE KO mice induced lipid-rich plaque, whereas treatment with DYSGT significantly inhibited the development of atherosclerosis." (PMID 24062791, 2013). "To further demonstrate the involvement of H2S in regulating CX3CL1 and CX3CR1 expression during atherosclerosis and to establish its pathophysiological relevance in vivo, we examined the effect of H2S on CX3CL1 and CX3CR1 expression in fat-fed apoE−/− mice." (PMID 22815945, 2012). "In this review, we focus on atherosclerosis- and hyperlipidemia-dependent ATLO neogenesis in aged ApoE−/− mice." (PMID 22783198, 2012). "The present results provide direct evidence that ginkgolide B represses atherosclerosis by attenuating P-selectin, RANTES, CD40L, and PF4 expression in plaque in ApoE−/− mice, with efficacy similar to aspirin." (PMID 22662117, 2012). "Compared with control ApoE−/− mice, animals with macrophage specific TGF-ß1 overexpression developed significantly less atherosclerosis after 24 weeks on the WTD (Western type diet) as indicated by aortic plaque area en face (p<0.05)." (PMID 22829904, 2012). "In fat-fed apoE−/− mice, H2S synthesis activity and CSE expression in the aorta gradually decreased and remained extremely low during the late stage of atherosclerosis." (PMID 22815945, 2012). "The -491SNP and -219SNP were related to different plasma apoE, LDL and cholesterol concentrations, and the risks of atherosclerosis and AD." (PMID 21549015, 2011). "Intranasal delivery of E-selectin prior to initiation of high-fat chow decreased atherosclerosis, serum total cholesterol, and expression of the leucocyte chemoattractant CCL21 that is typically upregulated in atherosclerotic lesions of ApoE−/− mice." (PMID 21701687, 2011).
atherosclerosis (continued). "Elimination of PF4 reduces atherosclerotic lesion size in ApoE−/− mice and disruption of PF4 and RANTES complexes can also reduce atherosclerosis in this mouse model." (PMID 20454664, 2010). "In addition, it is possible that the loss of PDZK1 in apoE KO mice might influence atherosclerosis and coronary heart disease via, as yet not identified, SR-BI-independent pathways." (PMID 19956623, 2009). "ApoE−/− mice injected with PCB-77 exhibited greater body weight, adipocyte hypertrophy, serum dyslipidemia, and augmented atherosclerosis." (PMID 18560532, 2008). "In separate studies, we injected ApoE−/− mice with vehicle or PCB-77 over a 6-week period and examined body weight, adipocyte size, serum lipids, and atherosclerosis." (PMID 18560532, 2008). "In contrast, the circulating leukocyte levels of MCP-1 were elevated in both the apoE−/− and transgenic mice, perhaps indicating different roles for blood leukocyte and vessel wall expressed MCP-1 in the low level apoE suppression of atherosclerosis." (PMID 18560564, 2008). "To elucidate the cellular and molecular mechanisms involved in pravastatin prevention of atherosclerosis, we investigated the impact of pravastatin on STAT3 activity in combating atherosclerosis in apoE-/- mice." (PMID 19330073, 2008). "Apolipoprotein E-deficient (Apoe−/−) mice with or without partial carotid artery ligation (PCAL) were used to model acute and chronic atherosclerosis." (PMID 41559687, 2026). "ApoE-/- mice were administered streptozotocin (STZ), fed with high-fat diet (HFD), and then treated with Orientin to test the efficacy of Orientin on ameliorating atherosclerosis through pathological and biochemical assays." (PMID 41891145, 2026). "This study investigated the impact of heparanase gene-deficiency on atherosclerosis development in non-diabetic and streptozotocin (STZ)-treated, diabetic apolipoprotein E gene knockout (ApoE-/-) mice fed a normal chow diet for eight weeks." (PMID 42290526, 2026). "The role of MCP-1, a pro-inflammatory chemokine, in atherosclerosis was explored in ApoE−/− mice lacking CCR2, which reduced lesion formation without affecting plasma lipids, linking MCP-1 to atherosclerosis development." (PMID 40001895, 2025). "The plaque area of advanced atherosclerosis was increased due to the absence of macrophage-specific SR-B1, while decreased by the overexpression of SR-B1 in ApoE−/− mouse models." (PMID 40872505, 2025). "ATL was found to block the progression of atherosclerosis and reduce inflammation in atherosclerosis-prone mice lacking apolipoprotein E (ApoE−/− mice)." (PMID 40862723, 2025). "Immunisation against P. gingivalis was able to mitigate pathogen-induced atherosclerosis in ApoE−/− but not in WT mice or on top of statins." (PMID 39957996, 2025). "Apolipoprotein E (APOE; OMIM # 107741) is involved in the pathogenesis of AMD, and is also responsible for other age-related or increasing age or aging disorders such as Alzheimer’s disease (AD) and atherosclerosis." (PMID 40625502, 2025). "Unlike ApoE-/- mice, moderate-intensity aerobic training did not reduce plaque area in mice with HIV-associated atherosclerosis." (PMID 40853965, 2025). "In experimental mice models, administration of Akkermansia muciniphila (an intestinal commensal with anti-inflammatory properties) to ApoE−/− mice reduced atherosclerosis due to decreased endotoxemia but did not affect neointima formation in ApoE3-Leiden mice." (PMID 39957996, 2025).
atherosclerosis (continued). "To corroborate that undetected alterations in haematopoietic cells of hIGFREO/ApoE−/− did not explain their reduced circulating leucocytes and atherosclerosis, we conducted bone marrow transplantation studies." (PMID 40171617, 2025). "Through the p38MAPK/p16 pathway, quercetin also inhibits macrophage senescence, which acts in a beneficial way in atherosclerosis treatment, improves lipid profiles, lowers dyslipidaemia, and reduces plaque size by 56% in studies using ox-LDL-stimulated macrophages and ApoE knockout mice." (PMID 41470139, 2025). "CVD assessed by atherosclerosis and aortic calcification was not exacerbated by the presence of either APOL1-G0 or APOL1-G1 variants in the ApoE-KO mice." (PMID 40459058, 2025). "Similarly, chronic Porphyromonas gingivalis infection in ApoE-null mice resulted in alveolar bone loss, aortic inflammation, and elevated systemic markers, such as serum amyloid A and oxidized LDL, highlighting the inflammatory pathway by which periodontal disease may influence atherosclerosis." (PMID 40001895, 2025). "Additionally, PKM2 knockout was found to reduce early atherosclerotic lesions in ApoE−/− mice, indicating the pivotal role of PKM2 in HHcy-mediated T cell activation and the progression of atherosclerosis." (PMID 39898976, 2025). "Consistently, CETP expression increased atherosclerosis in apoE-/- mice and enhanced SAA deposition in the aortic atherosclerotic lesions; however, there was no change in lesion development in apoE-/- mice deficient in SAA regardless of CETP expression." (PMID 40429677, 2025). "A recent study revealed that in ApoE-/- mice fed with a high-fat diet, collagen degradation detected by CHP primarily occurs within atherosclerotic plaques, and increases in parallel with the progression of atherosclerosis." (PMID 41152999, 2025). "Consistently, ATL had no protective effects against atherosclerosis in ApoE−/− mice lacking the FPR2 receptor." (PMID 40862723, 2025). "The effect of non-selective agonist WIN55,212-2 on atherosclerosis progression was investigated in ApoE-KO (ApoE−/−) mice." (PMID 40943579, 2025). "Neuropathological measures include CERAD neuritic amyloid plaque scores, Braak staging for tau pathology, arteriolosclerosis, atherosclerosis, cerebral amyloid angiopathy (CAA), microinfarcts, gross infarcts/lacunes, and APOE (apolipoprotein) ε4 carrier status." (PMID 41035071, 2025). "A study on mice lacking apolipoprotein E (Apo-E) and TP receptors suggested that atherosclerosis development benefits from TP receptor blockade." (PMID 41516038, 2025). "It has been documented that ATX in endothelial cells enhances atherosclerosis through the production of LPA 16:0 and LPA 18:0, and knockdown of ATX in endothelial cells reduces lesion macrophage accumulation, thereby reducing atherosclerosis in APOE−/− mice." (PMID 40018730, 2025). "Atherosclerosis areas were significantly increased in Trf2T188A/ApoE−/− vs. ApoE−/− mice, with no overall change in core or cap areas." (PMID 40493738, 2025). "Genetic inactivation or pharmacological inhibition of NEUs1 and 3, but not NEU4, significantly delayed the formation of fatty streaks in the aortic root, without affecting plasma cholesterol and LDL levels in ApoE−/− mouse models of atherosclerosis." (PMID 40943651, 2025). "ApoE prevents atherosclerosis progression, and lack of ApoE leads to spontaneous development of atherosclerosis." (PMID 38745947, 2024). "After 10 weeks on an atherogenic diet, ApoE−/− mice (n = 3) developed atherosclerotic plaques in the aortic root, while no visible signs of atherosclerosis were seen in the WT mice (n = 3)." (PMID 39201700, 2024).